TNF (tumor necrosis factor)
Diseases named in the same sentence as TNF in open-access papers (continued):
Sharing a sentence is not in itself a finding about the gene and the disease.
Hyperglycemia (continued). "It has been demonstrated that hyperglycemia causes the IL-6 and TNF-α increase; through the oxidative mechanism, research on diabetic patients has shown a significant association between IL-6, TNF-α, and diabetic nephropathy that can be used as indicators of diabetic nephropathy." (PMID 35685736, 2022). "We showed that hyperglycemia enhanced the proinflammatory response of M(IFNγ) to Hb-Hp complex uptake by stimulating the production of TNFα, IL-1β, IL-6, IL-8, and IL-1RA, supporting the observation that hyperglycemia itself can induce the secretion of proinflammatory cytokines." (PMID 35163309, 2022). "Moreover, in the pathological state of hyperglycemia and hemodynamic disorder, a large number of renal macrophages are infiltrated, and multiple inflammatory cytokines such as IL-1β, TNF-α, and IL-6 are released." (PMID 35355720, 2022). "For example, an exaggerated production of tumor necrosis factor (TNF-α) produced by monocytes as a response to hyperglycemia could exacerbate the metabolic and hormonal abnormalities of PCOS." (PMID 35456928, 2022). "Both hyperglycemia and TNF-α lead to impaired insulin signaling." (PMID 34572503, 2021). "In stroke models using diabetic rats, hyperglycemia increases neutrophil adhesion and transmigration, and also increases expression of TNF, IL-1β, E-selectin, soluble intercellular adhesion molecules (sICAMs), endothelial NO synthase (eNOS) and inducible nitric oxide synthase (iNOS)." (PMID 34054705, 2021). "Therefore, the impaired insulin signaling in the gastrocnemius muscles represents a mechanism for the induction of post-ischemic hyperglycemia through TNF-α-mediated IRS1 inhibition, with R-7050 improving this impairment." (PMID 34073455, 2021). "In addition, systemic inflammation and increased proinflammatory cytokines (e.g., tumor necrosis factor-α, interleukin-1, and interleukin-6) can lead to impaired insulin signaling, thereby exacerbating hyperglycemia." (PMID 34206813, 2021). "The effects of hyperglycaemia on TNFα expression were also strictly region-dependent." (PMID 34572059, 2021). "The inclusion of NAC increased the activity of mitochondrial complexes I and II + III as well as decreased the concentration of interleukin-1β, tumor necrosis factor α, and caspase-3, but only in the parotid glands of rats with hyperglycemia compared to the HFD group." (PMID 34753902, 2021). "In addition, this study presents the first comparative global analysis of intracellular versus extracellular proteomes of TNFα-stimulated HUVECs in the presence of hyperglycemia fractionated by cellular location (intracellular and extracellular spaces)." (PMID 34045516, 2021). "Moreover, TNF-α mediates various biological responses, including inflammation, infection, cell injury, and hyperglycemia." (PMID 34083930, 2021). "Notably, this drug prevents hyperglycemia-induced up-regulation of IL-1β, IL-6 and TNF-α in human endothelial cells and in aortic plaques from ApoE−/− mice." (PMID 33988232, 2021). "In addition, hyperglycemia can induce TNF-α production by M1 macrophages, and TNF-α levels are elevated in cutaneous wounds in diabetic rats." (PMID 34066746, 2021). "We could, therefore, compare the activities of both endogenous and exogenous protein profiles in hyperglycemia and TNFα-induced HUVECs." (PMID 34045516, 2021). "To investigate whether TNFα may regulate the expression levels of the KRIS proteins, we performed an in vitro study using endothelial cells as a target for TNFα under high glucose (hyperglycemia) condition." (PMID 34045516, 2021). "In conclusion, the present study demonstrated that chronic hyperglycaemia affects the expression of TNFα in a strictly regional and intestinal layer-dependent manner and it contributes to the region-specific damage of myenteric neurons and their environment in rats with type 1 diabetes." (PMID 34572059, 2021). "The other KRIS proteins were unaffected by exposure to hyperglycemia and TNFα treatment." (PMID 34045516, 2021).
Hyperglycemia (continued). "Furthermore, Müller cells have been reported to secrete increased amounts of VEGF and TNFα under stress conditions like inflammation or hyperglycemia, thereby promoting retinal inflammation." (PMID 34776983, 2021). "The present study is a first report to provide a complete global proteomic profile of TNFα-stimulated HUVECs in the presence of hyperglycemia with special emphasis on the investigation of the extracellular/secreted matrix proteome, considered of high importance in DKD." (PMID 34045516, 2021). "Evidence of increased oxidative stress is typically seen in the plasma and in the white adipose tissue of obese mice, in which the administration of ROS inhibitors improves hyperglycemia, hyperinsulinemia, and hyperlipidemia and reduces both ROS production and TNF-α expression." (PMID 34680177, 2021). "Therefore, the goal of this study is to reveal the effects of chronic hyperglycaemia and insulin treatment on TNFα expression in different gut segments and intestinal wall layers." (PMID 34572059, 2021). "Hyperglycaemia‐induced oxidative stress promotes inflammation through increased endothelial cell damage, microvascular permeability and increased release of pro‐inflammatory cytokines, including TNF‐α, interlukin‐1β (IL‐1β) and interlukin‐6 (IL‐6)." (PMID 33108705, 2020). "Esposito and colleagues revealed that TNF-α concentration was acutely increased by hyperglycemia in human subjects through an oxidative mechanism, and the excessive TNF-α is closely related to diabetic complications by inducing endothelial cell apoptosis under high-glucose condition." (PMID 32089705, 2020). "In order to obtain insight into the inflammatory processes induced by hyperglycemia, we examined the expression levels of four proinflammatory cytokines, namely, TNF-α, IL-6, IL-8, and IL-1α, under hyperglycemic conditions with or without anthocyanin-rich sour cherry extract." (PMID 33147748, 2020). "Hyperglycemia increased ROS, TNF-α and IL-6, and reduced miR-24 and miR-126 levels in plasma." (PMID 33680027, 2020). "Thus, PhyH, PhyF and quercetin increased MDA and TNF-α levels in normoglycemia while in hyperglycemia they exerted protective effects against oxidative stress and inflammation." (PMID 32824505, 2020). "Moreover, inflammatory markers and mediators such as c-reactive protein (CRP), interleukin-6 (IL-6) and TNF-α are present in systemic inflammation induced by hyperglycemia." (PMID 32932898, 2020). "As expected, these changes in protein expression were found to be concordant with the transcriptional modulations in cultured macrophages which displayed upregulated gene expression of M1 (CD11c, TNF-α, and IL-1β) and downmodulated M2 (IL-5) markers under constant or fluctuating hyperglycemia." (PMID 32806763, 2020). "TRAIL significantly reduced ROS formation in HAECs exposed to both TNF‐α and hyperglycemia." (PMID 33080110, 2020). "Using human aortic endothelial cells (HAECs), the primary objective of this study was to investigate the vasoprotective effects of TRAIL on the endothelium exposed to both hemodynamic (oscillatory shear stress, OSS) and humoral (TNF‐α, hyperglycemia) pro‐atherogenic stimuli." (PMID 33080110, 2020). "Hyperglycemia-induced ROS and AGEs production may stimulate the secretion of proinflammatory cytokines, such as TNF-α and IL-6, in renal tissues." (PMID 33447179, 2020). "Occurrence of hyperglycemia in the animals in this study may have contributed to a lower expression of the proinflammatory cytokine TNF-α at day 1 after wounding." (PMID 31859909, 2020). "TNFα may be considered a potential therapeutic target against aging-related disease in hyperglycemia." (PMID 32454945, 2020). "Importantly, hyperglycemia and mitochondrial ROS result in the oxidation of RIP1 and loss of executioner caspases prior to death receptor engagement by TNF-α." (PMID 33298902, 2020).
Hyperglycemia (continued). "The untreated cells exposed to hyperglycemia or hyperglycemia associated with quercetin or Physalis fruits extract showed the same levels of TNF-α without a statistical significance between the groups." (PMID 32824505, 2020). "Hyperglycemia may trigger inflammatory process elevating proinflammatory cytokines, IL-6 and TNF-α, expression, possibly due to ROS production or reduction of antioxidant defense systems." (PMID 31998774, 2020). "Administration of dopamine decreased hyperglycemia and serum TNF levels in endotoxemia." (PMID 30700738, 2019). "Thus, our data are in accordance with previous findings, since diabetic rats, with sustained hyperglycemia, exhibited both hyperalgesia and elevated TNF-α serum concentration levels." (PMID 31888677, 2019). "Future studies will be required to determine whether fenoldopam control of hyperglycemia contributes to modulate serum TNF levels." (PMID 30700738, 2019). "Our present results also suggest that fenoldopam attenuates hyperglycemia before the serum TNF peak at 1.5 h post-LPS, and thus the effects of fenoldopam on glucose may precede its effects on serum TNF levels." (PMID 30700738, 2019). "We observed that both hyperglycemia and glucose fluctuations induced polarization transitions to M1 phenotype in microglia, leading to increased expression of pro-inflammatory factors including TNF-α and IL-6." (PMID 31695681, 2019). "Besides increasing the oxidative stress level, hyperglycemia also increases proinflammatory cytokine levels, such as interleukin-6 and tumor necrosis factor (TNF)-α." (PMID 31514311, 2019). "Furthermore, hyperglycaemia-induced oxidative stress can also lead to the production of inflammatory factors such as TNF-α and IL-1β." (PMID 30838453, 2019). "Similarly, our current study verified that persistent hyperglycemia in diabetic rats was followed by increased TNF-α and IL-1β levels within kidney tissues, leading to a state of chronic, low-grade inflammation that intensified after I/R treatment." (PMID 31441362, 2019). "As we previously reported that splenectomy abrogated vagal control of TNF, we analyzed whether splenectomy also prevents vagal modulation of hyperglycemia." (PMID 30700738, 2019). "TNF-α is widely recognized to play a key role in T1D pathogenesis and onset of hyperglycemia." (PMID 31569489, 2019). "Compared with a previous study in monocytes, both consistent and intermittent hyperglycemia increased a more dramatic production of the inflammatory cytokines TNF-α and IL-1β in macrophages, and this proinflammatory effect is more pronounced in response to intermittent hyperglycemia." (PMID 29850615, 2018). "Hyperglycemia results in an increase in nuclear factor κB (NF‐κB) binding, which leads to increased production of inflammatory cytokines and chemokines, such as tumor necrosis factor (TNF) and monocyte chemoattractant protein (MCP‐1)." (PMID 30160055, 2018). "In addition to hyperglycemia, TNF-α (Th1 cytokine) also reported to directly induce SOCS3 expression." (PMID 29572460, 2018). "In primary human monocyte-derived macrophages, hyperglycemia induces the production of the prototype M1 cytokines tumor necrosis factor-α (TNF-α), interleukin-1β (IL-1β), and IL-6, but inhibits the M2 cytokines IL-1Ra and C-C motif chemokine ligand 18 (CCL18) during macrophage differentiation." (PMID 29850615, 2018). "Since an interaction between hyperglycemia and TNF-α on the induction of NETosis was observed in vitro, we examined whether this phenomenon was also evident in vivo by analyzing samples taken during the OGTT." (PMID 28659928, 2017). "Moreover, we have demonstrated that hyperglycemia-induced increases in TNF-α in REC and Müller cells can be effectively reduced by Compound 49b." (PMID 29095817, 2017). "This condition might be due to the release of the early neuropoietic cytokines like TNF-α, IL-1β, and IL-6 at the interphase of hyperglycemia induced biochemical changes and nerve damage." (PMID 28381989, 2017).
Hyperglycemia (continued). "Furthermore, TNF-α exerted an additive effect on NETosis induced by hyperglycemia in vitro in neutrophils isolated from normal healthy donors." (PMID 28659928, 2017). "Moreover, TNF-α expression in the infiltrating hepatic monocytes was enhanced in the DEREG chimeric mice with hyperglycemia compared to the WT or CCR2 KO chimeric mice with hyperglycemia." (PMID 27464894, 2016). "Hyperglycemia after severe TBI is associated with an increase in pro-inflammatory cytokines and pro-inflammatory transcription factors, such as transforming growth factor (TGF-β), interleukin 1β (IL1-β) and tumor necrosis factor-α (TNFα)." (PMID 27626493, 2016). "In addition, tumor necrosis factor-alpha, IL-1 beta, C-reactive protein, and other inflammatory factors can suppress the release of GnRH and LH in states of hyperglycemia." (PMID 27006953, 2016). "In studies using umbilical vein endothelial cells, fluctuant hyperglycemia could significantly increase the content of IL-6, TNF-α and ICAM-1 in vitro." (PMID 27496150, 2016). "Serum IFN-γ and TNF-α levels were significantly increased in mice with STZ-induced hyperglycemia." (PMID 27464894, 2016). "However, metabolic defects, such as hyperglycemia and oxidative stress, induce excessive proinflammatory cytokines (IL-1β, TNF-α, etc.)production, sustaining a prolonged influx of neutrophils and macrophages." (PMID 27057551, 2016). "The up-regulation of several hormones (glucagon, growth hormone, catecholamines, and glucocorticoids), inflammatory mediators (interleukin (IL)-1, IL-6, Intercelluar Adhesion Molecule (ICAM-1), and tumor necrosis factor (TNF)-alpha) accompanies the development of hyperglycemia." (PMID 27110221, 2016). "Studies demonstrated that TNF-α regulated quantity and function of glucose by decreasing levels of adipocyte-specific genes and increasing levels of preadipocyte-specific genes, contributing to insulin resistance and hyperglycemia." (PMID 27626493, 2016). "The result we have obtained may be in favor of beneficial effects of LLLT, since IL-6 reducing TNF-α level can therefore protect cells from the damaging effect of hyperglycemia." (PMID 26861982, 2016). "Hyperglycemia induced by glucose clamping in normal subjects showed a significant increase in the circulating levels of interleukin- (IL-) 6, IL-18, Il-1β, and tumor necrosis factor-α (TNF-α)." (PMID 27034691, 2016). "In addition, hyperglycemia, by itself, is known to augment the production of inflammatory cytokines such as tumor necrosis factor-α (TNF-α) and interlukin-6 (IL-6)." (PMID 26207186, 2015). "This response prevents TNF-α from interfering in insulin signalling and may prevent hyperglycaemia and metabolic disorder." (PMID 26512338, 2015). "Because we observed a difference in the p62 level between the NG and HG groups only in TNF-injected eyes, hyperglycemia may improve autophagic flux in TNF-induced optic nerve degeneration, although this may not occur in PBS-injected eyes." (PMID 26578885, 2015). "Short-term hyperglycemia protects axons against TNF-induced optic nerve degeneration." (PMID 26578885, 2015). "We have previously shown that TNFα levels are increased in hyperglycemia." (PMID 25888955, 2015). "We previously demonstrated that excessive hyperglycemia at levels of over 400 mg/dL for short-term periods, like 3 hr, did not evoke alterations of the gut microbiota, but apparently induced gut barrier dysfunction through TNF-α-dependent pathways." (PMID 26207186, 2015). "However, in spite of an initial rise at 12 hrs time-point following hyperglycaemia (approximately 2.5-fold for both these transcripts), at 48 hrs the level of such up-regulations were lower (1.5- and 2-fold increase for IL-6 and TNF-α respectively)." (PMID 25787249, 2015). "In conclusion, our present results suggest that short-term hyperglycemia protects axons in TNF-induced optic nerve degeneration and that this axonal-protective effect may be associated with autophagy machinery." (PMID 26578885, 2015).
Hyperglycemia (continued). "However, in the present study, the short-term hyperglycemia significantly inhibited TNF-induced upregulation of p62 protein levels in the optic nerve." (PMID 26578885, 2015). "In this study, we investigated whether short-term hyperglycemia prevents tumor necrosis factor (TNF)-induced optic nerve degeneration in rats and examined the role of autophagy in this axon change process." (PMID 26578885, 2015). "It has been suggested that cytokines, commonly increased during febrile diseases like interleukin-1 or tumor necrosis factor, may inhibit insulin release and increase the secretion of cortisol, further explaining hyperglycemia." (PMID 23741481, 2013). "Hyperglycemia induced p38 mitogen-activated protein kinase activation, leading to increased infiltration of macrophages and increased levels of interleukin (IL)-1, IL-6 and tumor necrosis factor-α." (PMID 24499158, 2013). "Most agents that promote inflammation activate NF-kB, including endotoxins, carcinogens, radiation, chemotherapy, hyperglycemia, tumor promoters, inflammatory cytokines [e.g., tumor necrosis factor (TNF), interleukin 1 (IL-1)], and growth factors such as epidermal growth factor (EGF)." (PMID 23805101, 2013). "Hyperglycemia induced degradation of inhibitory kappa B and reduced nuclear factor kappa B activation, leading to increased infiltration of macrophages and increased levels of proinflammatory cytokines, including interleukin-1 and tumor necrosis factor-α." (PMID 24027593, 2013). "Increase in TNF-α and IL-6 during diabetes may be due to hyperglycemia related to oxidative stress and inflammation." (PMID 23691290, 2013). "In STEMI-patients, several factors may contribute to glycocalyx damage, that is, ischemia-reperfusion injury, shock, inflammation (TNF-α), hyperglycemia, atrial natriuretic peptide and oxidized low density lipoprotein (LDL)." (PMID 23433357, 2013). "Both hyperglycemia and high fructose diet can directly produce ROS, which, subsequently, have been shown to stimulate TNF-α gene expression via the activation of the redox-sensitive NF-κB, a pleiotropic regulator of many “response-to-injury” genes, such as TNF-α." (PMID 23717483, 2013). "Hyperglycemia significantly increased TNFα and suppressor of cytokine signaling 3 levels." (PMID 23592917, 2013). "Previously, it has been suggested that hyperglycemia-induced ROS production led to renal dysfunction by activating NFκB, a common stress response gene, which, in turn, induced proinflammatory cytokines production including TNF-α and IL1-β." (PMID 23862157, 2013). "Thirdly, postchallenge TNF-α and nitrotyrosine levels at 2-hr, rather than hyperglycemia per se, were associated with the presence of CAD." (PMID 22397368, 2012). "However, TNF-α and nitrotyrosine induced by postchallenge hyperglycemia reached statistical significance in our study." (PMID 22397368, 2012). "This rapid decline in levels of endotoxin and TNF-α may be related to the changes in the microbiome and thus to the resolution of the hyperglycemia." (PMID 23119124, 2012). "Indeed, TNF-α and hyperglycemia have been shown to induce plasminogen activator inhibitor-1 (PAI-1) and vascular cell adhesion molecules (VCAM-1 and ICAM-1) expression in human vascular endothelial cells." (PMID 22973260, 2012). "Hyperglycemia induced the degradation of IκBα and NF-κB activation and as a result increased infiltration of macrophages (52%) as well as increased proinflammatory cytokines: TNF-α and IL-1β." (PMID 21663638, 2011). "Such a potentiating effect of high D-glucose was not restricted to IL-1β, as it was also observed for the pro-inflammatory cytokine TNF-α, whose levels are elevated in the circulation of diabetic patients and whose release to the circulation is promoted by hyperglycemia." (PMID 20386708, 2010).